TNF (tumor necrosis factor)
Diseases named in the same sentence as TNF in open-access papers (continued):
Sharing a sentence is not in itself a finding about the gene and the disease.
infection (continued). "Tumor necrosis factor (TNF) is responsible for the infiltration of neutrophils, which are key for the resolution of bacterial infections, and is one of the first proinflammatory ILs to be released within the first hour of infection." (PMID 34835359, 2021). "Furthermore, they have observed that inhibition of TNF-α leads to a delay in splenocyte apoptosis, suggesting there probably is a competition between the two cytokines during infection." (PMID 34790829, 2021). "Similarly, studies of TNF-α inhibitors, such as infliximab and etanercept, were terminated early due to infection-related mortality." (PMID 34068269, 2021). "ITAC, Fractalkine, IL-7, IL-8, and TNFα were identified as markers predictive for pre-infection." (PMID 33731158, 2021). "Despite M2 markers, the infection of these macrophages with Mtb demonstrated an atypical profile of response, with poor control of infection and similar release of immune mediators, such as IL-10, IL-1β, and TNF-α." (PMID 33921194, 2021). "In particular, TNF-α, G-CSF, and chemokines, normally key players in host responses to infection, are expressed at high levels in septic patients, where they trigger excessive inflammation that seriously damages cells and organs, and can ultimately lead to multi-organ failure and death." (PMID 34884813, 2021). "In such inflammatory responses, macrophages are known to play a role in host defense during the early stage of an infection by producing inflammatory mediators, such as nitric oxide (NO), interleukin-1β (IL-1β), interleukin-6 (IL-6), and tumor necrosis factor-α (TNF-α)." (PMID 34679773, 2021). "Supernatants were harvested 24 hr post-infection, and TNF was quantified by ELISA." (PMID 34755600, 2021). "However, IL-4 and TNF-α levels were decreased in the spleen of neutropenic animals 1-day post infection." (PMID 34642440, 2021). "The TNF-α and IL-6 levels gradually decreased with time post-infection." (PMID 33717010, 2021). "Our observations from in-vitro MΦ infection suggest a selective upregulation of Mincle that may rely on bacterial growth-dependent and -independent factors, as well as TNFα stimulation." (PMID 34320039, 2021). "While the pro-inflammatory action of eicosanoids is beneficial to the host at early stages of infection by promoting the intracellular killing of Mtb via induction of TNFα in infected macrophages, it may drive immunopathology at later stages of disease." (PMID 34951591, 2021). "Along with this observation, we also observed significantly lower levels of IL-6, IFN-γ, and CXCL-10 24 h post-infection, IL-17A and TNF-α 4 days post-infection, and IL-1β, CCL2 and CCL5 7 days post-infection in the lung of IL-38-treated mice, compared with mice without IL-38 administration." (PMID 33414457, 2021). "We hypothesized that MDMs produce high levels of TNF; however, during the virulent Mtb strain infection, it sheds from the cell surface, and consequently, the tmTNF levels are decreased, whereas those of solTNF are increased." (PMID 35008755, 2021). "Notably, these molecules except TNF-α were induced as early as 16 hours post-infection, peaked at around 36 hours post-infection, and significantly declined at 6 dpi." (PMID 34305887, 2021). "This in turn eludes to why such a series of triggers could lead to IL-6 and TNF-α production, dissemination of the infection and culminate in pathological situations as observed in MCL." (PMID 33765083, 2021). "Likewise, R. equi replication is reduced in equine monocyte derived macrophages primed with IFN-γ or TNF-α prior to infection." (PMID 34473814, 2021). "For the IRF5 rs3807306 risk allele and the TNF rs1799724 we observed a significantly lower allele frequency in ME/CFS patients without infection-triggered onset." (PMID 35046929, 2021). "Moreover, another cytokine IL-6 is also linked with the severity and death during human VL, which is due to the inhibition of TNF-α in the early stage of infection and consequently by inhibiting the Th1 responses." (PMID 33680991, 2021).
infection (continued). "IFN-γ, TNF-α, IL-1β, and IL-6 can promote inflammation when tissue injury or infection occurs." (PMID 33564301, 2021). "Whole-blood infection with C. albicans in either an active or inactive state induced a strong and comparable secretion of monocyte-derived cytokines (TNF-α, IL-1β and IL-6), whereas only low cytokine levels could be detected in mock-infected blood." (PMID 34103589, 2021). "We have previously shown that B6 mice deficient in TNFα succumb to Cp1038 infection much more rapidly than their normal B6 counterparts." (PMID 35174101, 2021). "The host response to infection could be regulated by TGFβ1 with the help of a cytokine storm and the presence of TNF, IL-1β, and IL-6." (PMID 33693030, 2021). "Finally, we used the model to explore how TNF impacts the infection dynamics during infection by a more- or less-infectious form of the virus." (PMID 34016976, 2021). "Furthermore, severe infections with SARS-CoV-2 are often associated with a cytokine storm resulting in high levels of IL-6 and TNF-α in the patients." (PMID 34122407, 2021). "Moreover, the selective inhibition of solTNF is another important target because it improves survival in an acute infection, nevertheless diverse signalling mechanisms for both forms of TNF, TNFR1 and TNFR2 receptors remain to be elucidated." (PMID 34067256, 2021). "Moreover, OROV infection led to the release of the pro-inflammatory cytokine tumor necrosis factor-alpha (TNF-α) and diminished cell viability 48 h post-infection, indicating that OROV triggers an inflammatory response and tissue damage." (PMID 34887719, 2021). "However, agonist treatment together with Δrgg3 infection resulted in decreased TNF-α production in response to lipopolysaccharide (LPS; TLR4), heat-killed Listeria monocytogenes (HKLM; TLR2), and CpG oligodeoxynucleotide (ODN1826; TLR9)." (PMID 33947757, 2021). "TNF levels were unchanged in immunized or not immunized mice after infection with the Gamma variant." (PMID 34960708, 2021). "THP-1, THP-FAKi (THP-1 treated with FAK inhibitor) and THP-FAK+ (THP-1 overexpressing FAK) macrophages were infected with Mtb and culture supernatants were collected at 24 hours post-infection to quantify the levels of TNF-α, IL-1β and IL-10 using the solid-phase sandwich ELISA." (PMID 34745115, 2021). "These cells produce distinct cytokines in response to infection, such as interleukin-12 (IL-12) and TNF, thus activating and stimulating other cell types, including NK cells, T cells, innate lymphoid cells (ILCs), and macrophages, which in turn, produce inflammatory cytokines such as IFN-γ." (PMID 33753412, 2021). "Confirming earlier results, infection increased the TNF-α secretion in PBMo more than in CBMo." (PMID 33924101, 2021). "This might explain why less chlamydial EBs or IFN-γ and TNF-α, could be detected in the lung homogenates of mice with initial mock infection 1 week after their secondary infection with serovar L2, compared with D or E." (PMID 34451996, 2021). "As such, TNF was discovered at the interface between infection and cancer." (PMID 35264975, 2021). "Moreover, in phorbol myristate acetate (PMA)-activated macrophages, TNF-α and IL-8 levels were significantly suppressed at the early stages post-infection." (PMID 34566910, 2021). "In addition, after challenge infection, we observed a reduction of IL-1β expression, and modulation of TNFα, TGFβ and IL10 expression." (PMID 33499363, 2021). "Furthermore, we have shown that OROV infection leads to an inflammatory response with increased TNF-α release, microglia activation markers, neuronal damage and loss of tissue viability." (PMID 34887719, 2021). "In conclusion, our data support that the transcriptional pathways analyzed by RNAseq are representative of both syncytia and non-fused trophoblasts and that PHT expressed pro-inflammatory cytokines independently of their fusion and infection status (at least for IL-6, IL-8, and TNFα)." (PMID 34367171, 2021).
infection (continued). "Recent findings showed that EVs released by T.cruzi-infected THP-1 cells activate TLR-2 and NF-kB pathway in recipient macrophages, resulting in enhanced production of pro-inflammatory cytokines (TNF-α, IL-6, and IL-1β) to maintain the inflammatory response in the course of infection." (PMID 34638604, 2021). "Furthermore, we suggest that extrinsic and intrinsic apoptosis caused by MO infection are associated with increased expression of proinflammatory cytokines, including IL-1β, IL18, and TNF-α." (PMID 34678131, 2021). "In this study, the relative expression levels of inflammatory cytokines TNFα, IL-8, IL-18, and IL-1β in IPEC-J2 cells along with the secretion of TNFα and IL-8 in the cell supernatant were significantly lower in the ΔhtpG infection group than those in the WT infection group." (PMID 34869065, 2021). "In addition, the level of TNF-α of MDR-MTB group at any time was similar to that of the infection group (P>0.05)." (PMID 35003120, 2021). "Pro-inflammatory cytokines, TNF-α and IL-6, are useful markers of infection severity." (PMID 34485172, 2021). "However, similarly to spleen cell cultures, decreased IFN-γ levels and increased TNF-α and IL-10 levels were observed in kidney cell cultures after 19 days of infection." (PMID 34575795, 2021). "In this model, there may be roles for both innate and adaptive TNFα, particularly as we see effects both early and late in infection." (PMID 35174101, 2021). "They produce cytokines such as IL-6 and TNF-α and are particularly active in case of infection." (PMID 33708198, 2021). "TNF production in immunized mice was reduced 10-fold after infection with the WT or Zeta variant; no significant changes were observed in immunized or nonimmunized mice after infection with the Gamma variant." (PMID 34960708, 2021). "Our work uncovers a central role of epithelium-autonomous NAIP/NLRC4 in eliciting a fine-tuned early response to the infection, thereby preventing the demise of the epithelial barrier, due to an overshooting pro-inflammatory TNF response in the intestinal mucosa." (PMID 33731826, 2021). "TNF-α is a cytokine composed of 157 amino acids, is produced after injury in macrophages, lymphocytes, neutrophils, and structural cells, and is stimulated by inflammation or infection." (PMID 34341362, 2021). "There was a significant increase in the TNFα mRNA level following infection with the ply deficient mutant but not the parent strain or the reconstituted mutant." (PMID 34046027, 2021). "In addition to VSV, resveratrol has been tested on the pseudorabies virus in piglets and resulted in increased production of antiviral cytokines, such as interferon-α and -γ, interleukin 12, as well as tumor necrosis factor-α after 7 days post-infection." (PMID 34204270, 2021). "Besides, TNF-α induces NETs release, or NETosis, whereby neutrophils release sticky extracellular traps that help limit the spread of infection." (PMID 34803441, 2021). "Using mRNA hybridization, we further show that uninfected bystander cells actively contribute to the resolution of infection by producing IL-6 and TNF-α, which, via paracrine signaling, activate IRF1/IRG1 and strengthen the antimicrobial activity of infected macrophages." (PMID 34607464, 2021). "IL-6 and TNF-α share of the ability to clear G. duodenalis in mouse infection models." (PMID 34238339, 2021). "Using randomly selected clinical isolates to infect THP-1 macrophages (five from early infections and five from chronic infections), we then measured mRNA levels of IL-1β, TNF, IL-8, and IL-10 through quantitative reverse transcription polymerase chain reaction (qRT-PCR) analysis." (PMID 33664232, 2021). "Although the basal luciferase activity of NF-κB was highly reduced in cells infected with both viruses, strong luciferase expression induced by TNFα was significantly inhibited after infection by rNiV and only moderately inhibited after infection by rNiV-W∆CTD." (PMID 34785771, 2021).
infection (continued). "Pathway analysis highlighted the involvement of transcriptional responses to core innate responses to pneumococci including modules associated with metabolic pathways activated in response to infection, oxidative stress responses and NFκB, NOD-like receptor and TNF signalling pathways." (PMID 34046027, 2021). "These mice additionally showed increased susceptibility to intranasal BCG, which again correlated with an impaired Th1-response, as manifested by diminished IFN-γ and TNF-α levels in the lungs, and with delayed and reduced mycobacterial-induced immune responses during early infection." (PMID 33679802, 2021). "The content of TNFα was significantly lower than that of the WT infection group (p < 0.05)." (PMID 34869065, 2021). "During infection, not only Stx is involved, but also different inflammatory cytokines and many of them are able to trigger neutrophils to release NETs, examples are LPS and TNF-alpha." (PMID 34944623, 2021). "We could show that upon infection, infected cells mount a strong pro‐inflammatory response characterized by a strong activation of the NFκB/TNF pathways while bystander cells mount an IFN‐mediated response." (PMID 33904651, 2021). "Our previous study showed that IL‐6 and TNF‐α levels in the bronchoalveolar lavage fluid of A(H1N1)pdm09‐infected mice were significantly higher than those in seasonal H1N1‐infected mice within 3 days after infection." (PMID 33470564, 2021). "On day four post-infection, the levels of pro-inflammatory cytokines TNF-α and IFN-γ were decreased to 6.6 and 2.5 times that observed in controls respectively while the levels of anti-inflammatory cytokine IL-10 and IL-4 were increased (by 2.1 and 5.7 times) upon quercetin treatment." (PMID 33803419, 2021). "Indeed, within several hours following infection, macrophages are able to produce and release a large amount of pro-inflammatory and Th1-type cytokines, such as tumor necrosis factor α (TNFα), interferon gamma (IFNγ) and interleukin-12 (IL12)." (PMID 34946140, 2021). "In line with this, we found that the number of PAKflic CFU was higher than that of PAK at 6 hours after infection, which might explain higher IL-1β and TNFα in BALF of PAKflic infected mice as compared to mice infected with PAK." (PMID 33793661, 2021). "It has been reported that the infection with SARS-CoV-2 can cause a cytokine storm in patients with symptoms severe or critical, consisting of an increase of IL-1β, IL-4, IL-6, IL-10, IL-17, TNF-α, G-CSF, GM-CSF, IFN-γ, CCL2, CXCL8, and CXCL10." (PMID 33917837, 2021). "Infection can stimulate the expression of pro-inflammatory genes, such as IL-6, TNF-α, etc., which can effectively eliminate microorganisms, accelerate tissue repair, and secret IL-10 and other anti-inflammatory cytokines to alleviate the inflammatory reaction." (PMID 33868293, 2021). "Interestingly, IL-8 secretion by infected macrophages significantly increased at 24 hours after infection and further increased at 28 hours after infection, whereas IL-6 and TNF-α gradually increased at 2–28 hours after infection." (PMID 33680221, 2021). "Although TNF-α concentrations may also reflect fetal antimicrobial defense against infection, TNF-α is known to increase during normal pregnancy and has also been recognized as a critical factor for placental development." (PMID 33898918, 2021). "Infection with NTS serovars is known to stimulate an enhanced Th1-type bias by CD4+ or CD8+ T cells associated with increased production of proinflammatory cytokines IFN-γ, IL-18, IL-12, IL-15, and TNF-α." (PMID 33956909, 2021). "As infection progressed in the vehicle controls, increased amounts of IL-6 and TNF-α, along with chemokines responsible for monocyte and neutrophil recruitment (CCL2, MIP-2a, and CCL4), were detected in the serum, and this pattern of inflammation was mirrored in the lungs." (PMID 34835277, 2021).
infection (continued). "Regarding the inflammatory cytokine contents in mice after infection, the contents of TNFα, IFNγ, IL-1β, and IL-18 in serum, spleen, and ileum of mice challenged with ΔhtpG strains were significantly decreased (p < 0.05) as compared with mice challenged with WT strains." (PMID 34869065, 2021). "When compared to the Mock/”X” control groups that encountered C.tr. for the first time 7 d before sacrifice, the IFN-γ and TNF-α levels were significantly decreased in all groups of animals that had already overcome a previous infection with either serovar 49 days before the secondary infection." (PMID 34451996, 2021). "Due to strong positive correlation between local TNF-α and IL-10 concentration and lung pathology, we hypothesize that these cytokines are involved in the induction of lung lesions during investigates infection." (PMID 33407470, 2021). "TNF-α is a pro-inflammatory cytokine, and it is responsible for the inflammatory insult that the body undergoes in response to infection, and therefore, therapies that inhibit TNF-α have been hypothesized." (PMID 34439967, 2021). "Morphological changes in bMECs, including swelling, shrinkage, necrosis and hematoxylin and eosin staining of cytoplasm, were apparent 4 to 8 h after infection with K. pneumoniae, but each bacteriophage significantly suppressed damage and decreased TNF-α and IL-1β concentrations." (PMID 33468111, 2021). "Tumor necrosis factor-alpha (TNF-α) has an important role in the early control of this infection." (PMID 34158982, 2021). "Over-secretion of TNF by the host in response to infection aggravates the disease." (PMID 34869718, 2021). "TNF-α, a proinflammatory cytokine, appears to have a crucial role in the regulation of infection." (PMID 34534548, 2021). "Accordingly, we showed that only CCHFV infection of moDCs induced a significant production of IL-6, IL-10 and TNF-α in comparison to the non-pathogenic HAZV." (PMID 33232320, 2020). "As a key regulatory cytokine, IL-10 may suppress over-expression of IFN-γ and TNF-α while permitting an immune response robust enough to eradicate infection." (PMID 32411624, 2020). "SUMO1-overexpressing macrophages also produced more TNF-α upon infection." (PMID 32994335, 2020). "Consequently, while infections seem to be responsible for reduced frequencies of IFNγ+TNFα+ co-expressing CD4+ T-cells in the first 2 years of life, an increase of triple producers is merely due to development." (PMID 32849561, 2020). "Our results indicate that infection with 98-124 strain induce a peak of systemic TNF-α at 2 dpi in mice and we observed also that TNF-α was downregulated in most of the IFN-treated group, with significantly lower levels in groups 2 and 5, those being also the ones with the lowest viremia levels." (PMID 32118067, 2020). "To test whether susceptibility could be explained by an overall deficiency in the intestinal immune response we analyzed gene expression for several infection-induced cytokines including TNF, IL-6, S100A, IL-18, and CXCL1." (PMID 32453761, 2020). "Since studies had reported that NH/P68 induced enhanced cytokine gene expression or production in macrophages compared to a virulent isolate, cytokine gene (IL-1β, IL-6, IL-10, IL-12p40, IL-18, TNF-α) expression in moMΦ after NH/68 or 22653/14 infection were monitored over-time." (PMID 32178332, 2020). "Since CXCL-8, IL-1β and TNF-α resulted as statistically significant overexpressed cytokines after 2h post infection, we analyzed their concentration at a protein level in supernatants of neutrophils infected with A. baumannii ATCC® 19606TM also 4 h after infection." (PMID 33253325, 2020). "TNF-α plays a crucial role in enhancing IL-12 production, and depletion of IL-12 leads to decreased production of interferon-γ and nitric oxide, resulting in exacerbation of infection." (PMID 32244903, 2020). "Amastigote infection alone did not cause significant changes in levels of TNF-α released by macrophages." (PMID 32640562, 2020).